PCNP (PEST proteolytic signal containing nuclear protein)
Description:
May be involved in cell cycle regulation.
Tractability: PROTAC: UniProt records ubiquitination sites on it; ubiquitination databases record sites on it; its protein half-life has been measured.
Gene: Protein-coding gene on chromosome 3 (101,574,180 to 101,594,465, forward strand). Ensembl gene ENSG00000081154.
Subcellular location: Nucleus
Subcellular location (Human Protein Atlas): Nucleoplasm; Nuclear bodies
Gene Ontology:
Molecular function: protein binding
Biological process: proteasome-mediated ubiquitin-dependent protein catabolic process; protein ubiquitination
Cellular component: nuclear body; nucleoplasm; nucleus
Genetic constraint (gnomAD): Loss-of-function variants: 4 observed, 10.74 expected, observed/expected ratio (o/e) 0.37, 90% interval 0.18 to 0.85. The upper end of that interval is the gene's LOEUF score, 0.85, which puts it in group 3 of 6, group 1 being the genes least tolerant of losing a copy. Missense variants: 124 observed, 137.56 expected, observed/expected ratio (o/e) 0.9, 90% interval 0.78 to 1.05. Synonymous variants: 46 observed, 50.32 expected, observed/expected ratio (o/e) 0.91, 90% interval 0.72 to 1.17.
Homologues: Orthologues: chimpanzee PCNP (99% identical), macaque PCNP (99% identical), dog PCNP (99% identical), pig PCNP (98% identical), mouse Pcnp (96% identical), rat Pcnp (80% identical), zebrafish pcnp (54% identical), zebrafish PCNP (52% identical).
Diseases named in the same sentence as PCNP in open-access papers:
PCNP is named in the same sentence as 19 diseases in open-access papers, as found by Europe PMC text mining. Sharing a sentence is not in itself a finding about the gene and the disease. The quoted sentences say what the papers report.
hepatoma (5 papers, 2018 to 2022). "It has been evaluated that PCNP shows mRNA transcription level similarity with CGREF1 in the regulation of the hepatoma cell cycle in the zebrafish hepatoma model." (PMID 35186732, 2022). "Recently, studies exhibit that mRNA of PCNP has been detected in some cancer cells, including U‐937 myeloid leukaemia cells, HepG2 hepatoma cells and HT‐1080 fibrosarcoma cells, suggesting the potential and promising relation of PCNP to other cancer cells including ovarian cancer cells." (PMID 32548978, 2020). "Recent studies indicate that PCNP mRNA has been detected in several cancer cells, including HepG2 hepatoma cells, U-937 myeloid leukemia cells, and HT-1080 fibrosarcoma cells, suggesting that PCNP may be involved in some aspects of tumorigenesis." (PMID 30872582, 2019). "Recent studies suggest that the mRNA expression of PCNP could be detected in several types of cancer, such as HepG2 hepatoma cells, HT-1080 fibrosarcoma cells, and U-937 myeloid leukemia cells, suggesting that PCNP may be involved in tumorigenesis." (PMID 30872582, 2019). "PCNP is involved in cell cycle regulation, and high levels of PCNP have been found in various cancer cell lines, including U-937 myeloid leukemia cells and HepG2 hepatocellular carcinoma cells, suggesting that PCNP may be engaged in carcinogenesis." (PMID 36703786, 2022). "In addition, it has been shown that PCNP mRNA can be detected in many types of cancer cells, such as HT-1080 fibrosarcoma cells, HepG2 hepatoma cells, and U-937 myeloid leukemia cells, indicating that PCNP might play an important role in cell proliferation and tumorigenesis." (PMID 29716528, 2018).
ovarian carcinoma (5 papers, 2020 to 2022). A malignant neoplasm originating from the surface ovarian epithelium. "Previous reports suggested that the PEST containing nuclear protein (PCNP) was demonstrated to be a tumor suppressor was associated with human cancers, including neuroblastoma, ovarian cancer and lung cancer." (PMID 36591491, 2022). "In many preclinical studies, it has been evaluated that PCNP expression has associations with the development and progression of various cancers like neuroblastoma, lung adenocarcinoma, and ovarian cancer." (PMID 35186732, 2022). "Through in vitro and in vivo experiments on ovarian cancer cells (SK-OV-3 and A2780) and xenografted nude mice models, it has been found that high expression of PCNP promotes the growth, migration, and invasion of ovarian cancer cells and inhibits apoptosis." (PMID 35186732, 2022). "Results of a recent novel study depicted that PCNP is involved in promoting ovarian cancer progression through activating the Wnt/β-catenin signaling pathway and epithelial–mesenchymal transition (EMT)." (PMID 35186732, 2022). "To preliminary investigate the role of PCNP in ovarian cancer, we utilized transcriptome landscape in TCGA which covers various kinds of genomic data with clinical information to analyse the expression level in cancer tissues compared with normal tissues." (PMID 32548978, 2020). "Herein, we first investigated the expression of PCNP in ovarian cancer tissues and cells, the effects of PCNP in ovarian cancer proliferation, apoptosis, migration and invasion, and determined the molecular mechanism of PCNP in ovarian cancer progression." (PMID 32548978, 2020). "Furthermore, studies confirmed the potential mediating role of PCNP in the proliferation, migration, and invasion of human neuroblastoma, lung adenocarcinoma cells, and ovarian cancer cells." (PMID 35186732, 2022). "Additionally, PCNP has been revealed to facilitate the progression of ovarian cancer through elevation of β-catenin nuclear accumulation and induction of epithelial to mesenchymal transition." (PMID 35468892, 2022). "The findings suggest that PCNP may be a regulatory protein upstream of the Wnt pathway involved in the occurrence and development of ovarian cancer and could act as a novel target for treating ovarian cancer." (PMID 35186732, 2022). "However, the role and underlying molecular mechanism of PCNP in ovarian cancer have not been plenty elucidated." (PMID 32548978, 2020). "In this study, we examined the effect of PCNP on OC cells proliferation, migration, invasion and apoptosis, showing that Wnt/β‐catenin pathway was severely affected by PCNP overexpression, and further regulate ovarian cancer tumorigenicity and development for ovarian cancer." (PMID 32548978, 2020).
lung adenocarcinoma (4 papers, 2019 to 2025). A carcinoma that arises from the lung and is characterized by the presence of malignant glandular epithelial cells. "Furthermore, PCNP expression was associated with T classification of lung adenocarcinoma." (PMID 30872582, 2019). "PCNP overexpression markedly promoted the growth of lung adenocarcinoma xenograft tumors, while PCNP knockdown notably reduced tumor growth." (PMID 30872582, 2019). "The results of Ki67 staining indicated that PCNP overexpression increased the in vivo proliferation of lung adenocarcinoma cells and a reverse effect was observed in the sh-PCNP group." (PMID 30872582, 2019). "Collectively, the results demonstrate that PCNP is involved in the regulation of the migration and invasion of human lung adenocarcinoma cells." (PMID 30872582, 2019). "The results indicated that PCNP overexpression notably decreased the apoptotic index and expression levels of cleaved caspase-3 and PARP, while PCNP knockdown significantly increased apoptosis, indicating that PCNP mediates mitochondria-dependent apoptotic pathway in human lung adenocarcinoma cells." (PMID 30872582, 2019). "In addition, our findings reveal that PCNP mediates the proliferation, migration, and invasion of human lung adenocarcinoma cells via STAT3/5 and PI3K/Akt/mTOR signaling pathways." (PMID 30872582, 2019). "In the current study, the expression level of PCNP in human lung adenocarcinoma was examined." (PMID 30872582, 2019). "Furthermore, PCNP can be a novel therapeutic target and potent PCNP inhibitors can be designed and developed in the treatment of lung adenocarcinoma." (PMID 30872582, 2019). "Previous studies have demonstrated that the expression of PCNP in myeloma and central nervous system cancer was significantly higher than that of normal tissues, and overexpression of PCNP promotes the proliferation, migration, and invasion of lung adenocarcinoma cells." (PMID 36703786, 2022). "However, the expression level of PCNP in lung adenocarcinoma is still unknown." (PMID 30872582, 2019). "A study published in Oncogenesis observed that PCNP is overexpressed in the human lung adenocarcinoma tissues more than in the corresponding adjacent non-tumor tissues." (PMID 35186732, 2022). "PCNP overexpression enhanced autophagy by increasing the expression levels of p-phosphatidylinositol 3-kinase (PI3K), p-Akt, and p-mammalian target of rapamycin (mTOR) in lung adenocarcinoma cells, however an opposite trend was observed in the sh-PCNP group." (PMID 30872582, 2019). "PCNP over-expression decreased apoptosis through up-regulating the expression levels of phospho (p)-signal transducers and activators of transcription (STAT) 3 and p-STAT5 in lung adenocarcinoma cells, whereas PCNP knockdown showed opposite trends." (PMID 30872582, 2019). "Our results suggested that PCNP overexpression promoted the level of CD31, whereas PCNP knockdown reduced the MVD in lung adenocarcinoma xenograft tumors, indicating that PCNP regulates the growth of human lung adenocarcinoma xenograft tumors through the mediation of angiogenesis." (PMID 30872582, 2019).
neuroblastoma (4 papers, 2018 to 2022). Neuroblastoma (NB) is the most common solid, extracranial childhood tumor. "Recently, PCNP gene-expression (downregulation and upregulation) association with the progression of human neuroblastoma was evaluated by using the SH-SY5Y and SK-N-SH cell lines." (PMID 35186732, 2022). "PCNP mediates the proliferation, migration, and invasion of human neuroblastoma cells through the MAPK and the PI3K/AKT/mTOR signaling pathways." (PMID 36591491, 2022). "Phosphorylations of PI3K (Tyr458/Tyr199), AKT (Ser473), and mTOR (Ser2448) decreased in the PCNP group and increased in the sh-PCNP group, suggesting that PCNP mediates the PI3K/AKT/mTOR signaling pathway in human neuroblastoma cells." (PMID 29716528, 2018). "PCNP mediates the proliferation, migration, and invasion of human neuroblastoma cells through mitogen-activated protein kinase and PI3K/AKT/mTOR signaling pathways, implying that PCNP is a therapeutic target for patients with neuroblastoma." (PMID 29716528, 2018). "Nevertheless, PCNP knockdown promoted the growth, migration, and invasion of neuroblastoma cells via increasing phosphorylations of PI3K (Tyr458/Tyr199), AKT (Ser473), and mTOR (Ser2448)." (PMID 29716528, 2018). "In addition, our previous study has demonstrated that PCNP could be detected in human neuroblastoma cells both at mRNA and protein levels." (PMID 30872582, 2019). "However, PCNP knockdown could promote the growth, migration, and invasion of neuroblastoma cells by decreasing phosphorylations of p38 (Thr180/Tyr182), JNK (Thr183/Tyr185), and ERK1/2 (Thr202/Tyr204)." (PMID 29716528, 2018). "Furthermore, PCNP over-expression significantly reduced the growth of human neuroblastoma xenograft tumors by down-regulating angiogenesis, whereas PCNP knockdown markedly promoted the growth of human neuroblastoma xenograft tumors through up-regulation of angiogenesis." (PMID 29716528, 2018).
colon cancer (3 papers, 2020 to 2025). "It has been previously reported that PCNP is a differential gene implicated in lymph node involvement during colon cancer." (PMID 35468892, 2022). "Notably, PCNP was discovered as a differentially expressed gene associated with lymph node involvement in colon cancer." (PMID 35468892, 2022). "In vivo experiments further verified that LINC00858 enhanced the tumorigenicity of colon cancer cells in vivo by regulating the RAD21/PCNP/STAT3/5 axis." (PMID 35468892, 2022). "It indicated the promoting role of LINC00858 in colon cancer progression though activating PCNP-mediated STAT3/5 pathway by recruiting RAD21." (PMID 35468892, 2022). "Next, we explored the involvement of the LINC00858/RAD21/PCNP axis in colon cancer pathogenesis." (PMID 35468892, 2022). "PCNP is known to be associated with cell cycle control and may be involved in tumorigenesis; however, no reports have suggested its role in colon cancer." (PMID 40457491, 2025). "Furthermore, we demonstrated that LINC00858 could upregulate PCNP transcription in colon cancer by recruiting the transcription factor RAD21." (PMID 35468892, 2022). "Another important finding of this study was that increased PCNP expression contributed to activation of the STAT3/5 pathway, which promoted the progression of colon cancer." (PMID 35468892, 2022). "Overall, the results obtained in the current study demonstrated that LINC00858 affects the progression of colon cancer and revealed that LINC00858 is able to recruit RAD21 to upregulate PCNP, which contributes to STAT3/5 signaling activation, thereby promoting the development of colon cancer." (PMID 35468892, 2022). "In order to study the effects of LINC00858 on the tumorigenicity of colon cancer cells by regulating the RAD21/PCNP/STAT3/5 axis in vivo, we injected SW480 cells transduced with adenovirus carrying oe-NC + sh-NC, oe-LINC00858 + sh-NC, oe-LINC00858 + sh-RAD21, oe-LINC00858 + sh-PCNP into nude mice." (PMID 35468892, 2022). "It is known that PCNP is related to control of the cell cycle and may be involved in tumorigenesis, however, to date there have been no reports suggesting a role for PCNP in colon cancer." (PMID 32345988, 2020).
COVID-19 (2 papers, 2021 to 2024). A disease caused by infection with severe acute respiratory syndrome coronavirus 2. "MRVI1 (also IRAG1) and PCNP were identified as potential causal proteins affecting risk of COVID-19 phenotypes in this study for the first time." (PMID 40303168, 2024). "In conclusion, our study identified proteins with evidence of causal association with different stages of COVID-19, including novel proteins such as KLC1, MRVI1, CACO2, and PCNP." (PMID 40303168, 2024). "Gene-based analyses identified five significant gene associations with COVID-19 positivity on chromosome 3 (p < 0.05/19,148 genes = 2.6 × 10−06): NXPE3 (p = 1.6 × 10−11), ZBTB11 (p = 5.8 × 10−11), CEP97 (p = 1.0 × 10−10), RPL24I (p = 9.4 × 10−09), and PCNP (p = 6.8 × 10−07)." (PMID 35222515, 2021).
rheumatoid arthritis (2 papers, 2017 to 2022). A chronic, systemic autoimmune disorder characterized by inflammation in the synovial membranes and articular surfaces. "Additionally, the expression of tumor necrosis induced protein 8-like 2 (TIPE2) and PCNP in peripheral blood mononuclear cells of active rheumatoid arthritis (RA) patient has abnormally increased, and there was a positive correlation between them." (PMID 36703786, 2022).
thyroid cancer (2 papers, 2022). "Overexpression of PCNP reduced the proliferation, migration, and invasion of human thyroid cancer cells and down‐regulation of PCNP showed reverse effects." (PMID 35813472, 2022). "Collectively, our findings reveal PCNP can mediate the proliferation, migration, and invasion of human thyroid cancer cells through MAPK and Wnt/β-catenin signaling pathways which finally contribute to the development of TC." (PMID 35813472, 2022). "In vivo and in vitro experiments deepen our understanding of the pivotal roles of PCNP in thyroid carcinoma progression and also provide new ideas for anti-cancer intervention." (PMID 35813472, 2022). "Overexpressed PCNP repressed the proliferation, migration, and invasion as well as cell cycle but promoted apoptosis and autophagy in thyroid carcinoma." (PMID 35813472, 2022). "In addition, PCNP regulated cell cycle arrest through modifications in the expression of cell cycle regulating genes and PCNP affected apoptosis via activation of ERK/JNK/p38 pathway in thyroid cancer cells." (PMID 35813472, 2022). "Furthermore, PCNP overexpression reduced the growth of xenografted human thyroid cancer, whereas PCNP knockdown showed opposite trends." (PMID 35813472, 2022). "Furthermore, PCNP expression was detected in thyroid cancer cells (TT, ARO, TPC-1, FTC-133) and the normal human thyroid cell line Nthy-ori3-1." (PMID 35813472, 2022). "In conclusion, in vitro and in vivo data demonstrate that PCNP as a tumor suppressor gene may serve as a novel prognostic and potential therapeutic marker in human thyroid cancer." (PMID 35813472, 2022). "In addition, overexpression of PCNP decreased human thyroid cancer cell proliferation, migration, invasion and xenografts, affected apoptosis by activating the ERK/JNK/p38 pathway, and influenced cell cycle arrest by altering the expression of genes that regulate the cell cycle." (PMID 36703786, 2022). "However, the role of PCNP in thyroid carcinoma still remains poorly understood." (PMID 35813472, 2022).
glioblastoma (1 paper, 2010). The most malignant astrocytic tumor (WHO grade IV). "Of particular interest was the specific expression of ATP6v0A1, STRADA, PCNP and CS transcript variants, analyzed in patients affected by glioblastoma, which confirmed all the predicted cassette exons, thus demonstrating the reliability of our computational analysis." (PMID 20813049, 2010). "The validation of the cassette exons specific for the nervous system, detected for ATP6v0A1, STRADA, PCNP and CS genes, prompted us to analyze their expression in patients affected by glioblastoma, the most frequent form of primary intracranial malignancy." (PMID 20813049, 2010).
lymph node metastasis (1 paper, 2022). "Additionally, logistic regression analysis revealed that high PCNP expression was a protective factor against lymph node metastasis, distant metastasis, and TNM staging." (PMID 36703786, 2022).
oral squamous cell carcinoma (1 paper, 2022). "However, the relationship between PCNP expression and the occurrence and development of oral squamous cell carcinoma (OSCC) requires further exploration." (PMID 36703786, 2022).
cancer (8 papers, 2018 to 2022). A tumor composed of atypical neoplastic, often pleomorphic cells that invade other tissues. "PEST-containing nuclear protein (PCNP), a nuclear protein, has been found to be associated with human cancers in recent years." (PMID 35813472, 2022). "By this reasoning, the mutation of PCNP may also cause the controversial roles of PCNP in some other cancers." (PMID 35813472, 2022). "Similarly, our results showed that PCNP over-expression significantly induced apoptosis by inhibiting phosphorylations of PI3K (Tyr458/Tyr199), AKT (Ser473), and mTOR (Ser2448), suggesting that PCNP-associated agents can be developed as anti-cancer drugs." (PMID 29716528, 2018). "Considering the importance and evidence of expression pattering in genes, this mRNA transcription similarity of PCNP with a protein involved in cell adhesion and proliferation predicts the PCNP role in cancer cell metastasis." (PMID 35186732, 2022). "Based on these depicted novel roles of PCNP in cell cycleregulation and of PCNP in tumorigenesis, it is logical to consider PCNP as a potential molecular target for cancer research." (PMID 35186732, 2022). "The findings of all preclinical studies on PCNP have established the fact that PCNP is the key regulatory protein in tumorigenesis and has the potential to be considered as a novel molecular target for designing drugs to treat cancer." (PMID 35186732, 2022). "PEST-containing nuclear protein (PCNP) has been found in the nucleus of cancer cells." (PMID 30872582, 2019).